METTL3 (methyltransferase 3, N6-adenosine-methyltransferase complex catalytic subunit)
Diseases named in the same sentence as METTL3 in open-access papers (continued):
Sharing a sentence is not in itself a finding about the gene and the disease.
cancer (continued). "Moreover, the METTL3–Snail–YTHDF1 axis can promote metastasis in malignant tumors with the modification of EMT-related mRNAs mediated by m6As, which leads to progression." (PMID 36675186, 2023). "Furthermore, we conducted additional investigations and observed that the cancer group displayed higher levels of METTL3 expression compared to the normal group." (PMID 37822880, 2023). "There are currently few studies on targeting METTL3 by ASO to delay cancer progression." (PMID 37095108, 2023). "First of all, m6A has been well-studied for its role in cancer, and the deposition in RNA are mainly mediated by a methyltransferase (i.e., Writers) complex, including METTL3, METTL14, WTAP, KIAA1459/VIRMA, ZC3H13, HAKAI and RBM15/15B, or METTL16 under existence of SAM." (PMID 37886684, 2023). "Thus, METTL3 regulates the fate of these RNAs through m6A modification at key transcripts, which in turn affects the development of many cancers, including hematologic malignancies and solid tumors." (PMID 36830614, 2023). "As the most widely known m6A writer, METTL3 is upregulated in distinct cancer types." (PMID 37965577, 2023). "Furthermore, METTL3 can participate in the immune regulation of various cancers by affecting the m6A modification of different immune-related genes." (PMID 36614956, 2022). "The controversial role of METTL3 in human cancer cells may be due to the different mechanisms of origin in various cancers." (PMID 35280730, 2022). "The positive staining of METTL3 could be found mainly in the nucleus, with higher expression in cancer tissues and lower expression in adjacent normal tissues." (PMID 36058919, 2022). "Finally, we discuss future directions and the potential for therapeutic targeting of METTL3 in cancer treatment." (PMID 36008936, 2022). "In most studies, METTL3 has been recognized as a potential oncogene in human cancers." (PMID 35574388, 2022). "METTL3 plays diverse roles in cancers; in most cases, it acts as an oncogene to promote the initiation and development of a variety of cancers, such as promotion of translation and RNA stabilization to regulate cell proliferation, migration, invasion, and chemoresistance." (PMID 35571106, 2022). "Furthermore, the association between METTL3 expression levels and disease-free survival (DFS) in patients with cancer was explored." (PMID 36614956, 2022). "METTL3, the first reported m6A reader, was identified as the main methyltransferase for the methylation process and was further proven to affect the development of many cancers 14-17." (PMID 35399719, 2022). "Extensive research has established that METTL3 is involved in cancer progression." (PMID 35436987, 2022). "Consequently, METTL3 is predicted to be an attractive therapeutic target for treating diseases, including cancers." (PMID 35571106, 2022). "We evaluated m-6-A modified protein, which showed IMPDH1 was closely related to m-6-A related regulatory proteins in pan-cancer, and we focused on evaluating the association of IMPDH1 with the top four proteins: YTHDF1, ALKBH5, YTHDF2, METTL3 in HCC, indicating a strong relationship." (PMID 36618420, 2022). "Notably, m6A-targeted transcription factors differed across cancer phenotypes, and further studies on the regulatory mechanism of action are necessary to develop more treatments targeting METTL3." (PMID 36517820, 2022). "In conclusion, alterations in METTL3 expression may significantly affect miRNA expression in various human cancers." (PMID 35992774, 2022). "Therefore, our results indicate that inhibition or deletion of METTL3 is potentially a new route fo ALT cancer therapy." (PMID 36399511, 2022). "However, the specific roles of METTL3 in various cancers are diverse and should be further explored in detail." (PMID 36614956, 2022). "Together, METTL3, as an important member of the m6A enzyme system, may play an essential role in cancer progression." (PMID 36058919, 2022).
cancer (continued). "The roles of methyltransferase-like 3 (METTL3), a core catalytic subunit, in various cancers remain unclear." (PMID 36614956, 2022). "We next investigated the expression of METTL3 in each type of cancer." (PMID 36614956, 2022). "Thus, dysregulated expression of METTL3 is an important factor affecting the survival of patients with cancer." (PMID 36614956, 2022). "Emerging evidence has suggested pharmacological inhibition of METTL3 might be a promising therapeutic approach for cancer treatment." (PMID 36289222, 2022). "Several hypotheses have been put forward whereby METTL3 overexpression in cancer promotes glycolysis, including multiple steps involved in glucose uptake and metabolism." (PMID 36289851, 2022). "Silencing METTL3 could reverse cancer cells’ resistance to radiotherapy/chemotherapy even though its biological effects were likely organ/lineage-specific." (PMID 36517820, 2022). "Some studies have confirmed that the overexpression of METTL3 may be an important factor in promoting the development of common malignant tumors in women." (PMID 35707365, 2022). "Conversely, the expression level of PTEN is increased after silencing METTL3 in cancer cells." (PMID 35053496, 2022). "Higher METTL3 expression levels are significantly associated with poor overall survival in ACC, KICH, and LIHC and poorer DFS in ACC, CESC, HNSC, KICH, and LIHC, supporting the potential of METTL3 as a prognostic biomarker in cancers, particularly in ACC, KICH, and LIHC." (PMID 36614956, 2022). "Notably, METTL3 has been reported to enhance the proliferation and migration but inhibit the apoptosis of several types of cancer cells." (PMID 35985997, 2022). "PDK4 collaborates with METTL3 to induce proliferation and hepatic chemosensitivity cancer cells." (PMID 35186927, 2022). "In addition, METTL3 has been proven to affect the resistance of human cancers to multiple drugs, including adriamycin, sorafenib, and gefitinib." (PMID 36428672, 2022). "Combining our studies with the results from databases, we can conclude that METTL3 is related to cancer prognosis at protein level, which strongly suggests that it could be a prognostic predictor." (PMID 36347025, 2022). "The key role of METTL3 in various cancers has also been reported." (PMID 36114893, 2022). "First, we analyzed the differential expression of METTL3 across cancer datasets." (PMID 35574315, 2022). "Second, the mRNA levels of METTL3 were used to explore its role in pan-cancer." (PMID 36614956, 2022). "RNA methylation (m6A modification) is mainly catalyzed by METTL3/METTL14 in human cancer cells." (PMID 35604883, 2022). "Studies have shown that m6A regulatory proteins can regulate m6A modification in ncRNA to produce various biological functions; for example, METTL3 can promote miR-221/222 processing and BC cell proliferation; in turn, ncRNA can also regulate m6A methylation of mRNA in cancer." (PMID 35628460, 2022). "In addition, when the data for all patients with cancer were combined, the results suggested that METTL3 expression levels were significantly higher in later stages than in earlier stages of disease." (PMID 36614956, 2022). "Our findings reveal a pivotal mechanism of METTL3-mediated HR and chemotherapeutic drug response, which may contribute to cancer therapy." (PMID 35502895, 2022). "METTL3 has been reported to regulate the expression of PD-L1 in various cancer types." (PMID 36212476, 2022). "In addition to FTO, the m6A writer METTL3 has also become a new target for anti-cancer drug development." (PMID 36360248, 2022). "The aberrant transcription of METTL3 has been reported in various cancer types." (PMID 35094011, 2022). "In CESC samples, METTL3 was overexpressed in cancer compared with the normal cervix." (PMID 35813476, 2022). "This supports an oncogenic role for METTL3 in PCa as reported in other cancer types." (PMID 36733939, 2022). "METTL3 has been known to upregulate the expression of MALAT1 in several cancer types." (PMID 36212476, 2022).
cancer (continued). "Recent studies clarified that METTL3 could participate in multiple diseases via regulating cancer cell proliferation, skeletal myoblasts, and embryonic development." (PMID 35210391, 2022). "METTL3 as the main methyltransferase has been found in many cancers, including ESCC." (PMID 35399719, 2022). "Our results suggest that the development of METTL3 inhibitors or targeting its pathway may lead to promising treatments for cancer patients." (PMID 35502895, 2022). "Moreover, the increased RNA methylation catalyzed by methyltransferase-like 3 (METTL3) was required for cancer development." (PMID 36120577, 2022). "To date, many studies have found that METTL3 regulated drug resistance in human cancers." (PMID 36167542, 2022). "METTL3 is one of the m6A writers and is involved in the development of various cancers." (PMID 35977935, 2022). "Studies have also reported on the key role of METTL3 in various cancers." (PMID 35012593, 2022). "Moreover, as a previous study revealed that METTL3 relocates in cytoplasm and exerts an m6A-independent function to regulate cancer progression, further researches are needed to investigate the functional complexity of METTL3 both in cytoplasm and nucleus." (PMID 36566195, 2022). "A previous study also showed that in human cancer, METTL3 could directly regulate the specific mRNA translation by recruiting eIF3 without coordinating with METTL14 and WTAP." (PMID 36371254, 2022). "In PCa, high expression of METTL3 elevates the growth and progression of cancer cells." (PMID 36011028, 2022). "According to a recent study, METTL3 plays a critical role in several forms of cancer." (PMID 36620557, 2022). "In pan-cancer analysis, EMT was significantly associated with METTL3 aberrant expression." (PMID 36614956, 2022). "Therefore, in different types of same cancer, owing to the differences in the expression of different “Readers”, METTL3 or METTL14 can have opposite effects in the same cancer type." (PMID 36561529, 2022). "Therefore, based on these current results, we believe that METTL3 plays an important role in multiple stages of cancer progression and ultimately affects prognosis." (PMID 36347025, 2022). "It will also illuminate how METTL3 regulates the expression of genes and pathways in various cancers, which may be useful in identifying novel therapies for cancer." (PMID 36008936, 2022). "Among them, METTL3 is studied the most, which showed a cancer-promoting role in HNSC." (PMID 36281789, 2022). "In bladder cancer, METTL3 was upregulated in patient samples, and it benefits cancer progression by mediating several m6A modification targets (CDCP1, ITGA6, AFF4, IKBKB, RELA, and MYC), in which YTH family served as the binding protein of the target transcripts." (PMID 35117988, 2021). "Hence, our findings underscore METTL3/ADAR1 axis as a novel crucial pathway in cancer progression that connects m6A and A-to-I editing post-transcriptional events." (PMID 33509238, 2021). "Previously, elevated METTL3 levels have been associated with malignant characteristics of cancer cells, but its role in TMZ resistance in GBM has not been fully understood." (PMID 34336690, 2021). "METTL3 exhibited its cancer suppressive role in CRC through regulating p38/ERK pathways." (PMID 33411363, 2021). "Moreover, accumulating evidence has elicited the ability of METTL3 to facilitate the EMT process in various types of cancers." (PMID 34666602, 2021). "Moreover, METTL3 has been reported to be upregulated or downregulated in certain cancers, and its specific roles in tumorigenesis remain controversial." (PMID 34335955, 2021).
cancer (continued). "It is highly possible that the inhibition of the metastatic ability of cancer cells after deletion of METTL3 may be mitigated by Snail’s overexpression." (PMID 34381012, 2021). "Given that there are multiple functions of METTL3 in human cancers, we also have reasons to investigate whether CircMEG3 inhibits the expression of Cbf5 dependent on METTL3 by reducing the methylation modification of Cbf5 mRNA." (PMID 33425489, 2021). "In bladder cancer, METTL3 promotes cancer development via the AFF4/NF-κB/MYC signaling network." (PMID 34295905, 2021). "In NPC, m6A-modified TRIM11 stabilized by METTL3 could inhibit cancer cell apoptosis to promote multidrug resistance and enhance cisplatin resistance in vivo." (PMID 34745970, 2021). "METTL3, the catalytic subunit of the m6A methyltransferase complex, plays a critical role on tumorigenesis, promoting cell proliferation, survival, and invasion of cancer cells." (PMID 33926465, 2021). "In addition, METTL3 functions as an oncogene or a suppressor gene in many types of cancers by affecting different m6A levels of target RNAs." (PMID 34631715, 2021). "METTL3 directly promotes translation of certain mRNAs by recruiting eIF3 in human cancer cells." (PMID 34150845, 2021). "Importantly, we found drastic differences when comparing our results with previously published METTL3 target proteins in other cancer cell lines, illustrating the high target specificity of m6A-modified proteins and rationality of the observed inconsistencies." (PMID 33676554, 2021). "Among them, METTL3 showed the most different mRNA levels between the normal and cancer tissues." (PMID 34178650, 2021). "And METTL3 is reported to be overexpressed in most human cancers." (PMID 34476262, 2021). "Reportedly, METTL3 is a vital regulator in malignant tumors." (PMID 33818282, 2021). "Furthermore, mechanistic studies of METTL3 in some types of cancer, such as ccRCC, HNSCC and TC, were incomplete." (PMID 33879256, 2021). "Recent studies suggest that METTL3 influences cell apoptosis in several cancer cells." (PMID 33759344, 2021). "Accumulating evidence has illustrated the pivotal roles of METTL3 in a variety of human cancers." (PMID 33879256, 2021). "Interestingly, METTL3 expression has been found to play a role in the regulation of cell growth-related pathways as well as cell death-related pathways in cancer." (PMID 34249924, 2021). "In osteosarcoma, low expression of FTO and METTL14 as well as high expression of METTL3 and YTHDF3 were associated with cancer metastasis and could be used as biomarkers to predict poor prognosis." (PMID 34345203, 2021). "In addition, METTL3 stimulates epithelial-mesenchymal transition (EMT) of cancer cells by stimulating receptor tyrosine kinase AXL, thereby enhancing the invasion and metastasis of OC." (PMID 34484284, 2021). "In pan-cancer, IGF2BP1 was a risk gene, while METTL3 was a protective gene." (PMID 34957092, 2021). "The m6A methylase, METTL3, has two‐way effects in different cancers." (PMID 33932138, 2021). "Elevated glycosphingolipid (particularly Gb3) in the glycosphingolipid-enriched microdomains (GEMs) of the cancer cell membrane due to increased glucosylceramide synthase (GCS) activated the cSrc/β-catenin signaling pathway which upregulated the METTL3 expression." (PMID 33814008, 2021). "Several recent reports suggest that METTL3 promotes cancer cell metastasis." (PMID 34094960, 2021). "Collectively, the inhibition or activation of METTL3 could also provide a new potential therapeutic strategy against cancer." (PMID 34381710, 2021). "METTL3 deficiency leads to a decrease in m6A, which blocks the EMT of cancer cells." (PMID 34277622, 2021). "METTL3, via m6A methylation, regulates the growth and renewal of cancer cells." (PMID 34093133, 2021).
cancer (continued). "Based on the diverse functions of METTL3, targeting METTL3 may bring a novel perspective for individualized therapy of cancer." (PMID 33879256, 2021). "It has been shown that METTL3 acts in the pathogenesis of various diseases, including cancers." (PMID 33061938, 2020). "As an important m6A methyltransferase, METTL3 is well studied in many types of cancers." (PMID 32808488, 2020). "The studies elucidated above suggest that METTL3 and its related pathways may become a reasonable therapeutic target for cancer patients with high glucose metabolism." (PMID 33552994, 2020). "Compared with the control group, expression levels of HNRNPC, YTHDF1, KIAA1429, RBM15, YTHDF2, and METTL3 in cancer group were significantly up-regulated (P < 0.05), while expression levels of FTO, ZC3H13, METTL14, YTHDC1, and WTAP in cancer group were significantly down-regulated (P < 0.05)." (PMID 33193582, 2020). "Importantly, RNA m6A modification mediated by METTL3 was currently detected to regulate various mRNA in many cancers 15,16,21-23, but its target genes in PCa still to be elucidated." (PMID 32284755, 2020). "Our studies also uncovered a synergistic effect of METTL3 KD and 2‐DG on cancer cell proliferation." (PMID 32068977, 2020). "The main reason for the dual role of METTL3 in cancer regulation may account for different targeted pathways and cancer heterogeneity." (PMID 32631107, 2020). "We evaluated the potential mechanisms responsible for the expression of Mettl3 in cancer cells." (PMID 32444598, 2020). "Whether this strategy could be applied for degrading METTL3 in cancers warrants further investigation." (PMID 32854717, 2020). "Growing evidence has suggested the implication of METTL3 in diverse human cancers." (PMID 32615646, 2020). "As noted herein, METTL3 is involved in different aspects of gastrointestinal cancer progression, including cancer cell proliferation, apoptosis, invasion, migration, metastasis, angiogenesis, radiochemotherapy resistance, glycolysis/lipid metabolism, and CSC maintenance." (PMID 32429972, 2020). "We presume that METTL3 is involved in a similar mechanism to other cancer types." (PMID 32201509, 2020). "However, METTL3 is upregulated in HCC and knockdown of METTL3 significantly inhibits the proliferation, migration and metastasis of cancer cells." (PMID 32898471, 2020). "Emerging evidence suggests that METTL3 has diverse functions in different cancers." (PMID 33090698, 2020). "Increasing evidence suggests that METTL3 is involved in the progression of cancer cells." (PMID 31991845, 2020). "Mettl3 also has been shown to be involved in cancer progression." (PMID 32483411, 2020). "The aberrant activity of m6A‐RNA methyltransferase METTL3 is involved in human cancers." (PMID 32615646, 2020). "Based on these data, we raised the hypothesis that the interaction between iASPP and METTL3 is required for apoptosis activation in cancer cells." (PMID 32201509, 2020). "In colorectal cancer (CRC), METTL3 promotes cancer cell migration and invasion by facilitating the biogenesis of miR-1246, which reverses the inhibition of the MAPK pathway through the downregulation of the tumor suppressor SPRED2, thus enhancing the metastatic capacity of CRC." (PMID 32443966, 2020). "Of note, the role of METTL3–METTL14 in some cancers remains controversial." (PMID 32296573, 2020). "The decrease of the METTL3 level can promote the apoptosis of cancer cells through MiR-33a." (PMID 33237039, 2020). "Both high expression of PDK4 and Mettl3 reduced the survival rate of cancer patients." (PMID 32444598, 2020). "Our study provided new insights into the role of METTL3 in the regulation of cancer progression." (PMID 33090698, 2020). "Prior studies suggest iASPP and METTL3 have a key role of tumorigenesis and prognosis of cancer." (PMID 32201509, 2020). "We hypothesized that the combination of iASPP and METTL3 would promote growth, invasion and migration via inhibiting apoptosis of cancer cells." (PMID 32201509, 2020).